INS (insulin)
Diseases named in the same sentence as INS in open-access papers (continued):
Sharing a sentence is not in itself a finding about the gene and the disease.
Insulin resistance (continued). "Glucose tolerance and insulin tolerance tests indicated that hepatic Rspo3 induction improved obesity-induced glucose intolerance and insulin resistance, respectively, in ob/ob mice, observations also made in DIO and KK-Ay mice." (PMID 39854351, 2025). "T2DM is characterised by a decrease in insulin secretion by pancreatic β-cells and the development of insulin resistance in the target tissues, including the liver, muscle and adipose tissues, which ultimately leads to hyperglycaemia." (PMID 40351422, 2025). "Insulin resistance, measured as the product of serum insulin by glucose level, has proven to be an adverse prognostic indicator of cardiovascular mortality." (PMID 40978759, 2025). "Type 2 diabetes (T2D), accounting for 90%–95% of DM cases, involves insufficient insulin secretion, impaired insulin action (insulin resistance), or both." (PMID 39959358, 2025). "It is known that greater blood insulin levels lead to insulin resistance, which in turn leads to weight gain, obesity and low SHBG concentrations." (PMID 40868462, 2025). "In the early stage of insulin resistance, pancreatic islet β cells maintain blood glucose homeostasis by secreting more insulin (i.e., the “compensatory phase”)." (PMID 40475963, 2025). "Elevated circulating insulin levels between 80 and 100 μU/mL characterize hyperinsulinemia, which often leads to metabolic disorders such as obesity, insulin resistance, and type 2 diabetes (T2D)." (PMID 40137469, 2025). "Chronically elevated insulin levels lead to insulin resistance, profoundly diminishing the vasodilatory properties of insulin." (PMID 40940776, 2025). "This condition is hallmarked by impaired metabolism of lipids, proteins, and carbohydrates, which contributes to the development of insulin resistance and impaired insulin secretion." (PMID 41464985, 2025). "HOMA-IR was positively correlated with HOMA-B in the LMM, reflecting a compensatory relationship between insulin resistance and insulin secretion." (PMID 40843316, 2025). "In this context, the triglyceride-glucose (TyG) index has emerged as a practical, non-insulin-based surrogate marker for insulin resistance." (PMID 41019336, 2025). "Adult patients with CAH exhibit elevated fasting plasma glucose levels, reduced insulin sensitivity, and a β-cell response that is unable to compensate for insulin resistance." (PMID 40529825, 2025). "Increased energy expenditure in response to IAA restriction may contribute to improved insulin sensitivity and decreased adipocyte number in white adipose tissue observed in pigs fed with R75, as low energy expenditure has been linked with increased insulin resistance and adiposity." (PMID 40431415, 2025). "Insulin resistance is a metabolic disorder characterized by a reduced cellular response to insulin, which disrupts glucose uptake and leads to complex metabolic and hormonal imbalances." (PMID 40002645, 2025). "Type 2 diabetes (T2D) is a chronic metabolic disorder characterized by insulin resistance and impaired insulin secretion, leading to persistent hyperglycemia." (PMID 40932616, 2025). "Taken together, these glucose and insulin dynamics support the use of the Matsuda Index as a sensitive marker of early insulin resistance in CF." (PMID 41300682, 2025). "After treatment with semaglutide, BMI, body weight, insulin, and Homeostatic Model Assessment for Insulin Resistance (HOMA-IR) values significantly decreased." (PMID 41141001, 2025). "Insulin resistance (IR), β-cell function (%B), and insulin sensitivity (%S) were estimated from fasting blood glucose levels and serum insulin levels." (PMID 41227734, 2025). "When the body experiences prolonged insulin resistance, elevated insulin levels can enhance insulin-mediated glucose metabolism in neurons, stimulate central nervous pathways in the brainstem, and lead to increased sympathetic activity." (PMID 41343443, 2025).
Insulin resistance (continued). "Insulin resistance results in elevated circulating insulin concentrations as a compensatory mechanism to maintain normoglycemia and prevent hyperglycemia." (PMID 41446289, 2025). "We believe this is related to the presence of insulin resistance in these groups, where circulating insulin inhibits the secretion of VLDL into systemic circulation through complex mechanisms such as the degradation of apolipoprotein B." (PMID 40084133, 2025). "Participating with phosphate metabolites, MI was involved in the complex insulin transduction network, and has been proved to alleviate insulin resistance and sustain metabolic homeostasis." (PMID 39803251, 2025). "Insulin resistance is acquired through a complex interplay of chronic inflammation, impaired insulin signaling, and altered lipid metabolism, all of which are interconnected." (PMID 40280905, 2025). "A significantly increased glucose intolerance, insulin resistance, increased fat pad mass/BW and decreased insulin secretion were reported in male 9.5 mos." (PMID 41516047, 2025). "Physiological assessments included body weight, fasting glucose, insulin, homeostatic model assessment for insulin resistance (HOMA-IR), serum lipids, sex hormones, angiotensin-converting enzyme (ACE) activity, and histological evaluation of cardiac tissue." (PMID 41464892, 2025). "Bimagrumab was shown to be effective in an RCT including adults with insulin resistance, demonstrating a -7.9% decrease in fat mass, +2.7% increase in lean mass, and improved HbA1c and insulin sensitivity after 10 weeks of bimagrumab treatment." (PMID 39929239, 2025). "Insulin resistance is defined as a reduced response of sensitive tissues to insulin stimulation, and it can be influenced by both genetic and environmental factors." (PMID 40906363, 2025). "In adipose tissue, profiling across insulin-resistance models shows attenuation of canonical insulin-responsive sites." (PMID 41373704, 2025). "These molecular observations suggest a maintenance of central insulin sensitivity despite peripheral insulin resistance in this PCOS mouse model." (PMID 40013621, 2025). "Type-2 diabetes (T2D) is a metabolic disorder of global magnitude, and originates from multi-organ insulin resistance, which amplifies the demand for insulin to eliminate glucose from the circulation." (PMID 41072794, 2025). "The various levels of insulin resistance and impaired insulin secretion are reflected in the OGTT glucose levels at the different time points." (PMID 40779219, 2025). "Chromium supplementation increases insulin sensitivity and significantly lowers insulin resistance, which in turn lowers free testosterone, fasting insulin, and body mass index (BMI)." (PMID 41141267, 2025). "After 12 weeks, both the high-fat diet (HFD) and low calcium diet (LCD) exhibited increased body weight and elevated serum insulin levels compared to the control group, indicating the development of insulin resistance." (PMID 40940347, 2025). "The DASH diet can enhance the activity of insulin signaling pathway and reduce insulin resistance, thereby reducing HbA1c level." (PMID 41229546, 2025). "Fasting glucose, fasting insulin, and insulin resistance (HOMA-IR; homeostatic model assessment of insulin resistance) decreased markedly in genistein recipients while remaining unchanged in the placebo group." (PMID 40076293, 2025). "Insulin resistance in muscle and liver, as well as alteration of insulin secretion by β pancreatic cells, can be considered as initial premises that are the central defects of T2D." (PMID 41012462, 2025). "In mHypoE-46 neurons, treatment with 10nM insulin for 6 hours, which is prior to the development of cellular insulin resistance, still resulted in significant downregulation of Igf1r, Irs1, and Irs2." (PMID 40105689, 2025).
Insulin resistance (continued). "Given the known inhibitory effects of inflammatory cytokines such as IL-6 and TNFα on insulin signaling, these findings suggest that SerpinA3k expression contributes to insulin resistance through proinflammatory mechanisms." (PMID 41329353, 2025). "In the context of obesity, chronic low‐grade inflammation can impair insulin signaling, leading to insulin resistance." (PMID 40658071, 2025). "Insulin resistance (IR) refers to the decreased efficiency of insulin in promoting glucose uptake and utilization." (PMID 40397902, 2025). "Given the role of GLP-1 in promoting insulin secretion and improving insulin resistance, the observed increase in GLP-1 provides a plausible mechanism for the improvements in HbA1c and insulin sensitivity." (PMID 40255516, 2025). "This cytokine-induced insulin resistance creates a vicious cycle, as hyperglycemia resulting from impaired insulin action can further promote inflammation." (PMID 39860000, 2025). "AMPK is crucial to enhancing insulin sensitivity, as its deactivation leads to an increase in insulin resistance." (PMID 40438603, 2025). "In our study, HFD-fed WT mice displayed clear signs of insulin resistance, evidenced by impaired glucose clearance following insulin injection." (PMID 40864772, 2025). "Traditional insulin resistance measures like fasting insulin or HOMA-IR are difficult to obtain during pregnancy, but TG/HDL offers a convenient alternative." (PMID 40625506, 2025). "In 68 study participants with euthymic BD, insulin resistance was assessed according to fasting glucose and insulin levels." (PMID 39579049, 2025). "E3 ligases primarily induce insulin resistance by driving ubiquitin‐mediated degradation of key upstream components of the insulin signaling cascade, with the IR and IR substrate proteins serving as primary targets." (PMID 41362701, 2025). "Studies have shown that PA leads to insulin resistance by directly impairing the insulin signaling pathway or inducing lipotoxicity, mitochondrial dysfunction, and inflammation." (PMID 39269560, 2025). "Both insulin and glucose rise significantly as beta-cell mass cannot promptly compensate for insulin resistance." (PMID 40568093, 2025). "Impaired insulin sensitivity (i.e. insulin resistance) is a major characteristic of type 2 diabetes and plays a significant role in the hyperglycaemia seen in these individuals." (PMID 40413649, 2025). "In normal-weight men with insulin resistance, android fat and total fat were significantly higher compared to insulin-sensitive normal-weight men." (PMID 41303786, 2025). "In this first part, we discuss the effects of nutraceutical compounds on insulin sensitivity and insulin resistance, T2DM, dyslipidemia, and MASLD in addition to diet and lifestyle interventions." (PMID 40431370, 2025). "TCEs activate the parasympathetic nervous system while inhibiting excessive sympathetic nervous activity, reducing the secretion of stress hormones such as cortisol and norepinephrine, improving insulin sensitivity, and reducing insulin resistance." (PMID 40778279, 2025). "Inflammation interferes with insulin signal transduction through blood and/or paracrine functions and leads to insulin resistance." (PMID 40070584, 2025). "The impact of the LCHF-KD on ER stress and insulin resistance is based on the alteration of substrate availability and utilization that, in turn, alleviates ER stress and enhances insulin signaling pathways." (PMID 41567335, 2025). "Accordingly, there is accumulating evidence from clinical studies investigating the effects of statins on insulin resistance and/or insulin secretion that statins can affect both." (PMID 39775321, 2025). "Since T2D is a polygenic disorder influenced by multiple genetic and environmental factors, SNPs play a crucial role in key biological pathways related to insulin secretion, insulin resistance, and glucose metabolism." (PMID 40362226, 2025).
Insulin resistance (continued). "Positive correlations with fasting glucose, HbA1c, and insulin point to its involvement in insulin resistance." (PMID 41357032, 2025). "Experimental mouse models support this, as IV injection of ADEVs derived from adipose tissue macrophages of obese mice into normal C57BL/6 mice leads to elevated insulin levels, insulin resistance, and impaired glucose tolerance." (PMID 40658727, 2025). "In summary, PCs participate in T2DM pathophysiology via multiple mechanisms, such as enhancing insulin secretion, safeguarding pancreatic β-cells, optimizing mitochondrial function and insulin resistance, and regulating hepatic lipid metabolism." (PMID 39995417, 2025). "This receptor mediates inflammatory pathways triggered by TNF-α, disrupting insulin signaling and promoting insulin resistance." (PMID 40153192, 2025). "Clinical parameters including HbA1c, fasting plasma glucose, insulin, and Homeostatic Model Assessment of Insulin Resistance (HOMA-IR) were assessed." (PMID 41301714, 2025). "Another study showed that Aβ acts as a competitive inhibitor of insulin, further contributing to insulin resistance." (PMID 41294899, 2025). "The worsening of obesity leads to insulin resistance, increasing the demand on pancreatic beta cells to produce and secrete insulin." (PMID 40561274, 2025). "The elevation of FFA in insulin resistance is due to combined resistance to insulin-mediated inhibition of adipose tissue lipolysis and decreased adipocyte capacity for fatty acid capture in insulin-resistant states." (PMID 40969373, 2025). "In scenarios of insulin resistance, low-grade inflammation plays a prominent role in the dysfunction of insulin signaling, mainly through cytokines like tumor necrosis factor-alpha (TNF-α) and interleukin-6 (IL-6)." (PMID 40563357, 2025). "Altogether, these observations point to a vertical upward shift in the dose-response curve of insulin on BGM in individuals with insulin resistance." (PMID 39185744, 2025). "When this microsystem is perturbed, brain hyperglycaemia, glucotoxicity and insulin resistance emerge and disrupt insulin signalling, a primary driver of cognitive impairment." (PMID 41460428, 2025). "Insulin resistance reduces normal lipid metabolism by impairing insulin’s inhibitory effects on hormone-sensitive lipase in adipocytes." (PMID 40227756, 2025). "The inflammatory response triggered by TLR activation alters insulin signaling, contributing to insulin resistance, a key feature of metabolic syndrome and type 2 diabetes." (PMID 40076851, 2025). "Insulin resistance (IR), defined as a systemic condition in which cells and tissues exhibit reduced responsiveness to the hormone insulin, affects multiple organs and regulatory pathways involved in metabolic homeostasis." (PMID 40427728, 2025). "Insulin resistance is a central feature in the pathogenesis of type 2 diabetes and refers to an impaired response to insulin in target tissues such as the liver, skeletal muscle, and adipose tissue." (PMID 41373704, 2025). "Insulin Resistance (IR) is a complex condition that leads to an impaired sensitivity to insulin in peripheral tissues." (PMID 40176892, 2025). "This is likely a consequence of physiological changes induced by insulin resistance, including reduced peripheral glucose uptake and elevated insulin demand." (PMID 39656436, 2025). "Insulin resistance is characterized by a deteriorated physiological response of peripheral tissues to the metabolic effects of insulin; and occurs due to a decrease in insulin receptor expression in tissues that play a role in energy homeostasis." (PMID 39879508, 2025). "Insulin resistance provokes increases in β-secretase activity, Aβ1–40/42 production, and Tau hyperphosphorylation through the insulin-dependent activation of the atypical kinase PKC-λ/ι in mice and monkeys." (PMID 40208460, 2025).
Insulin resistance (continued). "Leptin treatment prevented hepatic fat accumulation and insulin resistance, enhanced insulin and leptin signaling capacity, reduced orexigenic gene expression in the hypothalamus, and promoted browning of retroperitoneal adipose tissue." (PMID 40944384, 2025). "Prolonged exposure to 100 μg/kg/day BPA altered pancreatic insulin content and secretion, leading to postprandial hyperinsulinemia and insulin resistance in male mice." (PMID 40283944, 2025). "Fasting insulin concentration, insulin resistance and C‐reactive protein were higher while HDL‐C was lower in both the Ob and MASLD groups compared to the NW group." (PMID 40874510, 2025). "In turn, losing 5–10% of body weight improves insulin sensitivity, reduces insulin resistance, increases the number of spontaneous ovulations and reduces hyperandrogenism in this group of women." (PMID 40868249, 2025). "These factors significantly influence insulin signaling in insulin-responsive tissues, leading to systemic insulin resistance and hyperinsulinemia." (PMID 41327353, 2025). "NPs improve glucose metabolism through multiple pathways: activating insulin signaling, improving insulin resistance (IR), enhancing glycogen synthesis, inhibiting gluconeogenesis, and regulating gut microbiota homeostasis." (PMID 40363788, 2025). "One putative mechanism by which ginger enhances insulin sensitivity is via upregulation of adiponectin, an adipokine whose serum levels are typically reduced in obesity and insulin resistance." (PMID 40733199, 2025). "After 21 days of treatment with STZ, serum insulin and glucagon concentrations were measured to assess insulin resistance in all animals." (PMID 41463431, 2025). "It is important to note that older adults often compensate for insulin resistance in skeletal muscle, liver, and adipose tissue by secreting more insulin and are more prone to lipid metabolism abnormalities than younger individuals." (PMID 41357171, 2025). "The triglyceride-glucose (TyG) index, derived from the product of triglyceride (TG) and fasting plasma glucose (FPG) concentrations, has emerged as a non-insulin-based marker of insulin resistance in several studies." (PMID 40556832, 2025). "Excess adipose tissue can elevate the expression of inflammatory cytokines (such as TNF-α) and adipokines (like leptin and resistin), both of which contribute to the pathogenesis of insulin resistance by disrupting insulin signaling and action." (PMID 40724174, 2025). "Of note, the synthesis of muscle glycogen stimulated by insulin and the oxidation of glucose are suppressed in diabetic patients with chronic insulin resistance." (PMID 38397072, 2024). "We found that arsenic exposure decreased the glycogen content and reduced the glucose consumption in HepG2 cells, inducing liver damage in mice, as well as impaired glucose tolerance and insulin sensitivity, leading to hepatic insulin resistance." (PMID 39771098, 2024). "It is known that the two basic characteristics of T2DM include insulin resistance which then leads to insufficient insulin secretion." (PMID 37962815, 2024). "Type 2 DM is characterized by low insulin secretions from β-cells and peripheral insulin resistance, leading to elevated levels of fatty acids." (PMID 38339160, 2024). "Elevated FFA levels attributable to obesity precipitate insulin resistance, exacerbating impaired insulin signaling and attenuating insulin-mediated glucose uptake in skeletal muscle while augmenting hepatic glucose output." (PMID 39764243, 2024). "Chronic inflammation can interfere with the normal function of insulin, leading to insulin resistance; the release of inflammatory cells and mediators contributes to dysregulated lipid metabolism, increasing the risk of MetS." (PMID 38379861, 2024). "It has been shown that vitamin D can improve insulin resistance by increasing the capacity of healthy pancreatic β cells to secrete insulin." (PMID 38321509, 2024).